SLITRK4 (SLIT and NTRK like family member 4)
Description:
It is involved in synaptogenesis and promotes synapse differentiation. Suppresses neurite outgrowth (By similarity).
Synonyms: DKFZp547M2010
Tractability: Small molecule: it belongs to a druggable protein family. Antibody: UniProt places it where antibodies can reach, with high confidence; its Gene Ontology location is reachable by antibodies, with high confidence; UniProt predicts a signal peptide or a membrane-spanning region. PROTAC: its protein half-life has been measured.
Gene: Protein-coding gene on chromosome X (143,622,790 to 143,636,101, reverse strand). Ensembl gene ENSG00000179542.
Subcellular location: Membrane; Cell membrane
Pathways (Reactome):
Neuronal System: Receptor-type tyrosine-protein phosphatases
Gene Ontology:
Molecular function: protein binding
Biological process: regulation of synapse organization; axonogenesis; positive regulation of synapse assembly
Cellular component: glutamatergic synapse; plasma membrane; membrane
Homologues: Orthologues: chimpanzee SLITRK4 (99% identical), macaque SLITRK4 (99% identical), dog SLITRK4 (98% identical), mouse Slitrk4 (97% identical), rat Slitrk4 (97% identical), pig SLITRK4 (97% identical), rabbit SLITRK4 (90% identical), tropical clawed frog slitrk4 (85% identical), zebrafish slitrk4 (73% identical). Paralogues in human: SLITRK5 (44% identical), SLITRK2 (43% identical), SLITRK6 (41% identical), SLITRK3 (41% identical), SLITRK1 (33% identical), SLIT1 (18% identical), SLIT2 (17% identical), SLIT3 (17% identical), TLR9 (16% identical), LRRC70 (14% identical), GP5 (14% identical), LINGO1 (13% identical), and 13 more.
Diseases named in the same sentence as SLITRK4 in open-access papers:
SLITRK4 is named in the same sentence as 20 diseases in open-access papers, as found by Europe PMC text mining. Sharing a sentence is not in itself a finding about the gene and the disease. The quoted sentences say what the papers report.
hepatocellular carcinoma (4 papers, 2020 to 2025). A malignant tumor that arises from hepatocytes. "However, this is also supported by the overexpression of SLITK4 in leiomyosarcoma and the identification of SLITRK4 as a causative gene in chronic myelocytic leukemia and hepatocellular carcinoma." (PMID 38736483, 2024). "In hepatocellular carcinoma, miR-139-5p can regulate the proliferation, migration and invasion of hepatocellular carcinoma cells by targeting different targets such as SLITRK4, CCT5 and ARF6." (PMID 35386287, 2022).
fragile X syndrome (2 papers, 2020 to 2023). A genetic syndrome caused by mutations in the FMR1 gene which is responsible for the expression of the fragile X mental retardation 1 protein. "There is a report on Iranian patients with an altered expression of SLITRK4 associated with fragile X syndrome caused by a repeat expansion in the 5′ untranslated region of the FMR1 gene at the same chromosomal location." (PMID 37891789, 2023). "Genes which regulate axon growth and pathfinding as well as terminal branching of axons such as SEMA3C and SLITRK2 and SLITRK4 were found downregulated in iNeurons from patients with Fragile X syndrome, an ID disorder associated with epigenetic dysregulation." (PMID 32562237, 2020).
gastric cancer (2 papers, 2025). A primary or metastatic malignant neoplasm involving the stomach. "We further investigated the role of SLITRK4 in other cancer types, which suggested that overexpression of SLITRK4 significantly increased the mortality risk of gastrointestinal cancer, including CRC and gastric cancer." (PMID 39499724, 2025). "In gastric cancer, CNPY3 enhances liver metastasis by forming a regulatory axis with SLITRK4, which drives endocytosis and recycling of the TrkB receptor, ultimately fostering metastatic potential." (PMID 40055606, 2025).
schizophrenia (2 papers, 2019 to 2024). A major psychotic disorder characterized by abnormalities in the perception or expression of reality. "Second, function-damaging mutations have been identified in SLITRK4 in patients with schizophrenia patients." (PMID 38736483, 2024). "For example, mutations of SLITRK4 have been recently linked to schizophrenia through a synaptic dysfunction mechanism." (PMID 31371714, 2019). "Broad expression of Slitrk4, including the cerebral cortex, and mildly decreased prepulse inhibition in Slitrk4 KO mice may be in line with its involvement in schizophrenia pathophysiology." (PMID 38736483, 2024).
Anxiety (1 paper, 2024). Intense feelings of nervousness, tension, or panic often arise in response to interpersonal stresses. "Although rodents with social avoidance behavior are often accompanies with increased general anxiety and depression-like behaviors, depression-like behavior may not be clear in Slitrk4 KO mice." (PMID 38736483, 2024).
colon adenocarcinoma (1 paper, 2025). "As a result, SLITRK4 expression was positively correlated with the level of macrophage infiltration in colon adenocarcinoma (COAD)." (PMID 39499724, 2025).
colorectal cancer (1 paper, 2025). A primary or metastatic malignant neoplasm that affects the colon or rectum. "This study indicates that SLITRK4 plays a newly pro‐oncogenic role in exacerbating colorectal cancer (CRC) tumorigenesis and metastasis." (PMID 39499724, 2025).
dyslexia (1 paper, 2005). A learning disorder characterized by an impairment in processing written words. "Furthermore, a recently identified dyslexia susceptibility locus on Xq27.3 includes the SLITRK2 and SLITRK4 genes, which belong to the SLIT and NTRK-like family of genes involved in mouse neurite outgrowth and show high homology to Slit proteins." (PMID 16254601, 2005).
myotonic dystrophy type 1 (1 paper, 2024). Steinert disease, also known as myotonic dystrophy type 1, is a muscle disease characterized by myotonia and by multiorgan damage that combines various degrees of muscle weakness, arrhythmia and/or cardiac conduction disorders, cataract, endocrine damage, sleep disorders and baldness. "SLITRK4 can rescue neurite outgrowth deficits in myotonic dystrophy type 1 (DM1) patient-derived cells, and its expression is downregulated in the neural cells and brains of DM1 patients, suggesting its clinical importance in DM1." (PMID 38736483, 2024).
tumor (5 papers, 2020 to 2025). "Assessment of gene expression in tumor infiltrating cells by scRNA‐seq confirmed that SLITRK4 caused significant changes in the TAMs and T‐cell populations in the tumor." (PMID 39499724, 2025). "Furthermore, the results from coculture models and single‐cell RNA sequencing analyses suggested SLITRK4 promoted tumor‐associated macrophages (TAMs) infiltration and polarization." (PMID 39499724, 2025). "Considering the potential regulation of cytokine production, we further evaluated the correlation of SLITRK4 with tumor‐infiltrating lymphocytes via Tumor Immune Estimation Resource (TIMER)." (PMID 39499724, 2025). "siSLITRK4‐NPs treatment led to obvious decrease in SLITRK4 expression and a reduction in Ki‐67‐positive tumor cells in liver metastases." (PMID 39499724, 2025). "Combined with the present results, we, therefore, hypothesized that high expression of SLITRK4 is correlated with monocyte‐derived macrophage infiltration and polarization, which may further contribute to the immune escape of tumor cells." (PMID 39499724, 2025). "Inhibition of SLITRK4 significantly suppresses CRC liver metastasis by modulating cell‐matrix adhesion, reducing angiogenesis and tumor‐associated macrophage infiltration in the tumor microenvironment." (PMID 39499724, 2025). "Finally, a small interfering RNA targeting SLITRK4 encapsulated into a lipid‐polymer hybrid nanoparticles platform (siSLITRK4‐NPs) significantly suppressed CRC tumor growth and liver metastasis." (PMID 39499724, 2025). "This is primarily because SLITRK4 physically interacts with the tumor suppressor Ptprd." (PMID 38736483, 2024). "Consistent with the observation in vitro, when SLITRK4‐knockdown SW620 cells were implanted, the tumor growth rate was slower than that of the control in vivo, otherwise, SLITRK4 overexpression resulted in significantly higher proliferation." (PMID 39499724, 2025). "Therefore, targeting SLITRK4 may trigger effective remodeling of the TME to an anti‐tumor state." (PMID 39499724, 2025). "Furthermore, using SLITRK4‐knockout and SLITRK4‐overexpressing CRC cell lines and mouse models, we confirmed that SLITRK4 exerted protumorigenic effects by enhancing tumor growth, invasion, and liver metastasis." (PMID 39499724, 2025). "Multiple in vitro and in vivo models suggested SLITRK4 promoted CRC tumorigenesis, invasion, migration, and angiogenesis, and inhibition of it restrained CRC tumor growth and liver metastasis with a more profound effect on the tumor microenvironment (TME)." (PMID 39499724, 2025). "In conclusion, our study showed that the miR-139-5p expression was decreased in HCC tumor samples, which could increase HCC invasion and proliferation capacity by increasing SLITRK4 expression." (PMID 32285917, 2020). "Here, our study showed that the miR-139-5p expression was decreased in HCC tumor samples, which could increase HCC invasion and proliferation capacity by increasing SLITRK4 expression." (PMID 32285917, 2020).
cancer (2 papers, 2021 to 2025). A tumor composed of atypical neoplastic, often pleomorphic cells that invade other tissues. "Using the coculture system, we further confirmed that SLITRK4 expression in cancer cells is related to TAMs infiltration and polarization." (PMID 39499724, 2025). "Unfortunately, the role of SLITRK4 and MLEC in cancer has not been illustrated yet." (PMID 33442423, 2021).
nervous system disease (1 paper, 2020). "Until now, only a few studies have reported the function of SLITRK4, many of them are related to nervous system disease, and our study is the first time to explore the function of SLITRK4 and its correlation to the progression of HCC." (PMID 32285917, 2020).
SLITRK4 also shares sentences with these, for which no sentence is quoted: bipolar disorder (1 paper); breast carcinoma (1); chronic myelocytic leukemia (1); depression (1); Dystonia (1); leiomyosarcoma (1); phobia (1); psychiatric disorder (1).